PIK3CA (phosphatidylinositol-4,5-bisphosphate 3-kinase catalytic subunit alpha)
Diseases named in the same sentence as PIK3CA in open-access papers (continued):
Sharing a sentence is not in itself a finding about the gene and the disease.
colorectal cancer (continued). "Our aim was to explore the clinical, molecular and pathologic characteristics of incident PIK3CA-mutated colorectal carcinomas from a large prospective cohort study." (PMID 23785428, 2013). "In summary, we have found that PIK3CA mutation in colorectal carcinomas correlated with tumor proximal colonic location, mucinous differentiation, KRAS mutation, high levels CIMP and loss of MGMT expression." (PMID 23785428, 2013). "In summary, PIK3CA-mutated colorectal carcinomas are more likely to develop in the proximal colon, to demonstrate high levels of CIMP, KRAS mutation and loss of MGMT expression." (PMID 23785428, 2013). "We investigated associations between PIK3CA mutation and other molecular markers of colorectal carcinoma." (PMID 23785428, 2013). "Colorectal cancer patients with PIK3CA mutations compared to wt PIK3CA demonstrated a trend to a shorter median PFS to the last FDA-approved therapy (2.8 months [1.6-4.0] vs. 4.3 months [3.3-5.3]; p=0.10)." (PMID 23248156, 2012). "Colorectal cancer was the largest tumor-specific subgroup, consisting of 24 patients with PIK3CA mutations and 48 matched wt PIK3CA controls." (PMID 23248156, 2012). "Univariate and multivariate logistic regression model for clinical characteristics associated with PIK3CA mutations in colorectal cancer." (PMID 22675430, 2012). "In conclusion, we show that KRAS and PIK3CA mutations are frequently associated in patients with colorectal cancer." (PMID 22675430, 2012). "To assess the association between PIK3CA mutations and different clinical features in patients with colorectal cancer, we tried to fit univariate and multiple logistic regression models." (PMID 22675430, 2012). "KRAS and PIK3CA mutations frequently coexist in patients with colorectal cancer, and are associated with clinical characteristics and outcome." (PMID 22675430, 2012). "Role of KRAS, BRAF and PIK3CA mutations in pathogenesis of colorectal cancer (CRC) has been recently investigated worldwide." (PMID 22931052, 2012). "For instance, mutations in KRAS are effective predictors of colorectal cancer patients’ responses to cetuximab, and mutations in PIK3CA are correlated with resistance to cetuximab treatment in colon cancer cell lines." (PMID 22994622, 2012). "In disease-specific sub-analyses, we found a lower survival in patients with colorectal cancer and PIK3CA mutations who, compared to wt PIK3CA patients, experienced a shorter OS-Ph1 (3.6 months vs. 10.3 months; p=0.001)." (PMID 23248156, 2012). "This study investigates the prevalence of loss of PTEN expression and mutations in both PTEN and PIK3CA in colorectal cancers (CRC) and their associations with tumour clinicopathological features, lifestyle factors and dietary consumptions." (PMID 21473780, 2011). "In colorectal cancer specifically, the pik3ca gene is mutated in 20–25% of CRCs while pik3ca mutations occurring in the hotspots located in exon 9 and exon 20 are oncogenic in CRC cell models." (PMID 21203412, 2010). "In a recent study, PIK3CA mutations were found to serve as surrogate markers for poor survival in colorectal cancer patients." (PMID 21103049, 2010). "In colorectal cancer, activation of the PIK3CA pathway can result either from activating PIK3CA mutations or from inactivation of the PTEN protein." (PMID 21139621, 2010). "These cells were derived from a human colorectal cancer containing one mutant (H1047R) and one normal allele of the PIK3CA gene." (PMID 21179398, 2010). "In comparison to the reported 14% frequency of PIK3CA mutations in colorectal carcinomas in the COSMIC database, the current series shows only 4% mutations." (PMID 21103049, 2010). "Furthermore, in PIK3CA-mutated colorectal cancer, GPT2-mediated generation of α-KG from glutamine is indispensable for cell growth." (PMID 41323791, 2025).
colorectal cancer (continued). "Colorectal cancers with PIK3CA mutations exhibited higher total tumor mutation burdens (TMBs) compared to their unmutated counterparts, highlighting the frequent presence of PIK3CA gene mutations and suggesting potential for developing combination targeted therapies." (PMID 40535798, 2025). "In PIK3CA-mutated colorectal cancer, GPT2-derived α-KG from glutamine is essential for cell growth." (PMID 41323791, 2025). "Additionally, GPT2 is upregulated by PIK3CA mutation and increased phosphatidylinositol 3-kinase α (PI3Kα, encoded by PIK3CA) through PDK1-RSK2-ATF4 signalling axis in colorectal cancer cells." (PMID 40943457, 2025). "Co-mutations in BRAF and PIK3CA may signify an aggressive phenotype, as both mutations correlate with poor outcomes in colorectal cancer." (PMID 40502411, 2025). "In conclusion, the impact and mechanism of PIK3CA gene mutation on tumor-associated antigen vaccines or cell therapy in colorectal cancer is complex, involving multiple aspects such as tumor cells, immune cells, signaling pathways, and the tumor microenvironment." (PMID 39555098, 2024). "PIK3CA gene mutation is one of the most common molecular alterations in colorectal cancer." (PMID 39555098, 2024). "Clinical applications of PIK3CA mutations in colorectal cancer." (PMID 39555098, 2024). "Multi-hit PIK3CA colorectal cancer; PIK3CA variant allele frequencies." (PMID 39401325, 2024). "Fourthly, the application of PIK3CA gene mutations in individualized treatment of colorectal cancer is still in its early stages, and more clinical trials and evidence are needed to verify its effectiveness and safety, as well as to optimize its treatment regimens and guiding principles." (PMID 39555098, 2024). "It is worth noting that different types and locations of PIK3CA gene mutations may also have different impacts on the prognosis of colorectal cancer patients." (PMID 39555098, 2024). "PIK3CA gene mutations have various impacts on the biological behavior of colorectal cancer cells." (PMID 39555098, 2024). "There is evidence that patients carrying PIK3CA mutations may benefit from treatment with acetylsalicylic acid, commonly known as aspirin, particularly in the setting of colorectal cancer." (PMID 35780223, 2022). "PIK3CA mutations reprogram glutamine metabolism by upregulating GPT2 in colorectal cancer cells." (PMID 35804447, 2022). "Also, aminooxyacetate (AOA) suppresses tumor proliferation of colorectal cancer with PIK3CA mutations by inhibiting enzymatic activity of GPT2." (PMID 35804447, 2022). "Moreover, compared with the COSMIC cohort, PIK3CA mutations in most cancer types except for large intestine cancer and lung cancer were more concentrated at hotspots mainly involving E545K, E542K and H1047R in the Chinese cohort." (PMID 35778737, 2022). "Interestingly, these POLE mutations were predominantly associated with KRAS, NRAS, BRAF, and/or PIK3CA mutations, commonly found in colorectal cancers." (PMID 35624529, 2022). "Notably, compared with the COSMIC cohort, PIK3CA mutations in most cancer types except for large intestine cancer and lung cancer were more concentrated at hotspots in the Chinese cohort." (PMID 35778737, 2022). "This investigation examines colorectal cancer cell lines bearing BRAF mutations with concomitant PIK3CA mutations and compares them to BRAF mutant cell lines without PIK3CA mutations in regard to genomic characteristics such as ploidy, MSI status, and coexisting molecular alterations." (PMID 36295658, 2022). "BRAF and PIK3CA mutations are observed in a subset of colorectal cancers." (PMID 36295658, 2022). "However, the presence of PIK3CA mutations in BRAF mutated colorectal cancers leads to a numeric increase in the prevalence of MSI (from 59.5% to 68.2% in TCGA and from 47.1% to 62.9% in the DFCI cohort)." (PMID 36079062, 2022).
colorectal cancer (continued). "It has been suggested that PIK3CA mutations may be a long-sought biomarker for successful adjuvant therapy with aspirin in colorectal cancer patients." (PMID 33237662, 2021). "PIK3CA is a high-frequency mutation gene in colorectal cancer, while its prognostic value remains unclear." (PMID 33842311, 2021). "Mutations in exon 9 and 20 of PIK3CA are closely related to colorectal cancer." (PMID 34976987, 2021). "However, the relationship between PIK3CA mutations and the prognosis of colorectal cancer patients remains controversial." (PMID 33237662, 2021). "Oncogenic PIK3CA could regulate cell motility though AKT, and PIK3CA mutations played key roles in reprograming glutamine metabolism in colorectal cancers." (PMID 32117908, 2020). "However, there were some controversial issues in these studies, especially among those studies that focused on esophageal, gastric, and colorectal cancers with different gene mutation types, such as PIK3CA, that have survival benefits." (PMID 32646396, 2020). "In addition, while CANCER mice carry mutations in the Apc and Pik3ca genes, and the homologs of these genes are often mutated in human colorectal cancers, many other genes have also been associated with the disease." (PMID 32170841, 2020). "However, the mechanism by which aspirin has a better therapeutic effect on colorectal cancer with PIK3CA mutation is unclear." (PMID 32000660, 2020). "In conclusion, based on the results of this study, aspirin can improve OS and CSS in patients with colorectal cancer after diagnosis, especially in those with PIK3CA gene mutations and high PTGS2 (COX-2) gene expression, but it cannot improve OS in patients with esophageal cancer and gastric cancer." (PMID 32646396, 2020). "The PIK3CA gene encoding catalytic subunit p110α was mutated in about 10% of colorectal cancers." (PMID 32000660, 2020). "Exon 9 (E545K) is the most frequently mutated hotspot in PIK3CA in colorectal cancer (CRC)." (PMID 32099598, 2019). "A recent study reported PIK3CA mutation frequency of 14% in Belgian colorectal cancer patients." (PMID 31905960, 2019). "Finally, the percentages of PIK3CA mutations were higher in colorectal-cancer samples which had mTOR-pathway activation (9/27, 33%) than in colorectal-cancer samples without mTOR-pathway activation (6/44; 14%; χ2 p=0.0484)." (PMID 29137436, 2017). "Our current study further investigated 13 commonly used colon cancer cell lines and two isogenic cell lines with heterozygous knock-in of either of PIK3CA mutations c.3140A>G (p.H1047R) and c.1633G>A (p.E545K), both of which are commonly observed in colorectal carcinoma." (PMID 29152088, 2017). "PIK3CA c.3140A>G (p.H1047R) and c.1633G>A (p.E545K) mutations are common in colorectal carcinomas." (PMID 29152088, 2017). "Based on an interesting study of aspirin efficacy in colorectal cancer, we hypothesized that celecoxib antitumoral activity may be restricted to PIK3CA mutated BC." (PMID 27835884, 2016). "Given the role of microRNA and PIK3CA in carcinogenesis, we hypothesized that genetic variations in the PIK3CA 3′-UTR may confer individual susceptibility to colorectal cancer." (PMID 25834816, 2015). "In summary, our findings indicated that miR-520a/PIK3CA axis may be involved in colorectal carcinogenesis, and rs141178472 polymorphism in PIK3CA 3′-UTR may contribute to colorectal cancer risk." (PMID 25834816, 2015). "In addition, 2 patients (both with colorectal cancer) had a different PIK3CA mutation in the FFPE tumor samples (Q546P and E545D/M1043L, which were not included in the BEAMing panel)." (PMID 25980577, 2015). "PIK3CA (exon 9 and 20) mutations have been described in 15–18% of colorectal cancers." (PMID 26090613, 2015). "The prevalence of PIK3CA mutations in patients with colorectal carcinoma may vary between 7% and 32%." (PMID 25834816, 2015).
colorectal cancer (continued). "Considering a possible role for PIK3CA mutation as a predictive biomarker of response to adjuvant aspirin therapy in colorectal cancer, our finding may be of interest." (PMID 24885062, 2014). "Therefore, therapeutics targeting the PI3K pathway can potentially benefit the subpopulation of colorectal cancer patients harboring the PIK3CA mutation." (PMID 23826249, 2013). "Finally, Liao and colleagues found that the chronic use of aspirin lengthens survival in individuals with mutated-PIK3CA colorectal cancer, possibly by inducing apoptosis via PIK3CA inhibition." (PMID 23965959, 2013). "KRAS, BRAF and PIK3CA mutations are commonly found in colorectal cancers." (PMID 23617638, 2013). "Considering the important functions of CSCs, it is interesting to explore whether therapeutic agents targeting the PI3K/mTOR signaling pathway are effective in colorectal cancer driven by CSCs harboring a somatic PIK3CA mutation." (PMID 23826249, 2013). "PIK3CA mutations occur in 20 to 30% of human colorectal cancers." (PMID 23593290, 2013). "KRAS, BRAF and PIK3CA mutations are frequently observed in colorectal cancer (CRC)." (PMID 23671647, 2013). "We detected PIK3CA mutation in 14% of colorectal carcinomas." (PMID 23785428, 2013). "Mutations in PIK3CA are present in 10 to 15% of colorectal carcinomas." (PMID 23785428, 2013). "PIK3CA mutations are associated with resistance to cetuximab in colorectal cancer in vitro." (PMID 22994622, 2012). "In addition, mutations in KRAS, BRAF and PIK3CA are associated with a worse outcome in patients with colorectal cancer." (PMID 20098682, 2010). "However, PIK3R1 and PIK3CA mutations co-occur in endometrial and colorectal cancers, suggesting that these double events may contribute to pathogenesis in particular tumor types." (PMID 39858051, 2025). "Therefore, PIK3CA gene mutations may be a predictive factor for immune checkpoint inhibitors and can be used to screen colorectal cancer patients suitable for immunotherapy." (PMID 39555098, 2024). "Therefore, the relevance of PIK3CA gene mutations to the clinical characteristics of colorectal cancer requires further research and validation to clarify the impact of different mutation types and locations on the clinical characteristics of colorectal cancer." (PMID 39555098, 2024). "Therefore, the prognosis and survival value of PIK3CA gene mutations in colorectal cancer are influenced by multiple factors, including the detection method of mutations, the types and locations of mutations, the coexistence of mutations, and the clinical characteristics of patients." (PMID 39555098, 2024). "In addition, different types and locations of PIK3CA gene mutations may also have different effects on the clinical characteristics of colorectal cancer." (PMID 39555098, 2024). "The PIK3CA gene is a well-known oncogene that harbours activating mutations in multiple types of human neoplasia including both benign and malignant breast neoplasia as well as many other epithelial and mesenchymal cancer types such as colorectal carcinomas and angiosarcoma." (PMID 36635367, 2023). "The present study found that patients in the PI3K/Akt-MT group of the immunotherapy cohort had a higher frequency of mutations in the PIK3CA gene, which suggests that PIK3CA mutations may improve the prognosis of colorectal cancer patients receiving ICI therapy." (PMID 35707003, 2022). "Five patients achieved a confirmed tumor response including 1 complete response and 4 partial responses (PR), among whom 4 patients had PIK3CA mutations in the dose-expansion stage and one colorectal cancer patient had unknown PIK3CA mutation status in the dose escalation stage." (PMID 36385120, 2022).
colorectal cancer (continued). "Therefore, PIK3CA mutations could be regarded as an effective pharmacogenomic feature in predicting aspirin effectiveness in colorectal cancer patients." (PMID 36545311, 2022). "However, the relationship between PIK3CA mutations and the prognosis of colorectal cancer patients remains unclear." (PMID 33237662, 2021). "Therefore, PIK3CA mutations appear to be a promising biomarker; however, they reported that more studies are needed to precisely define the effect of somatic mutations in the PIK3CA gene in the treatment of colorectal cancer patients." (PMID 33237662, 2021). "In colorectal cancer, exon 9 plays a more important role than exon 20, whereas in endometrial cancer, the opposite pattern was described, suggesting that different mutations of PIK3CA may have specific effects on downstream carcinogenic signals." (PMID 30782187, 2019). "Interestingly, recent clinical trials have strongly highlighted that low-dose aspirin (100 mg/day) can act as therapy in colorectal cancer patients positive for PIK3CA mutations and who have undergone surgical resection in terms of reducing the risk of recurrence." (PMID 31905960, 2019). "Given the relatively low frequency of PIK3CA mutations (10–20%) in colorectal cancer, it is unlikely that an effect on the mutated PIK3CA tumours alone could explain the large effects of aspirin on colorectal cancer incidence and mortality observed in the randomised vascular trials." (PMID 23589726, 2013). "In PIK3CA-mutant colorectal cancer lines, copanlisib, another class 1 selective inhibitor, has been shown to increase apoptosis, decrease cell growth, and decrease phosphorylated AKT expression in cells." (PMID 40564038, 2025). "In colorectal cancer, oncogenic activation of PIK3CA polarizes cell metabolism towards glutamine mobilization, hence constituting a putative therapeutic approach." (PMID 40038309, 2025). "Dysregulation of PI3K signaling, often through mutations in PIK3CA, loss of PTEN, or hyperactivation of AKT, is implicated in various cancers, including breast, ovarian, and colorectal cancers, as well as cutaneous malignancies." (PMID 40227764, 2025). "MLN0128 treatment also showed a decrease in colorectal cancer organoid size and a reduction in size of PIK3CA-mutant colon tumors in vivo." (PMID 40564038, 2025). "Through genomic technology, the identification of specific mutations in genes associated with the development of colorectal cancer, such as KRAS, BRAF, and PIK3CA, can be performed." (PMID 40083375, 2025). "PIK3CA alterations are also frequently detected across cancer types, including ovarian (17.14%), urothelial (11.54%), and colorectal cancer (11.43%), reflecting its known role in PI3K pathway dysregulation." (PMID 40649709, 2025). "The role of PIK3CA mutation and PTEN status in mediating EGFR‐directed therapy resistance in colorectal cancer is still unclear." (PMID 40302146, 2025). "For colorectal cancer, we were able to analyze the effect of mutation-CNV co-occurrence on patient prognosis for three genes, namely APC, FBXW7, and PIK3CA." (PMID 41415395, 2025). "In colorectal cancer (CRC), PIK3CA mutations have been shown to reprogram glutamine metabolism by upregulating glutamate pyruvate transaminase 2 (GPT2), thereby increasing tumor cell dependence on glutamine." (PMID 41425618, 2025). "Higher PIK3CA protein expression was observed in normal rectal tissue than in colorectal cancer tissue." (PMID 38891994, 2024). "MiR-375 was also connected to regulate the expression of PIK3CA in the colorectal cancer cell culture model." (PMID 39768623, 2024).